RN7SL504P (RNA, 7SL, cytoplasmic 504, pseudogene)
Gene: Miscellaneous RNA gene on chromosome 3 (51,872,178 to 51,872,464, forward strand). Ensembl gene ENSG00000241789.
Homologues: Orthologues: chimpanzee Metazoa_SRP (98% identical), macaque Metazoa_SRP (91% identical), guinea pig Metazoa_SRP (60% identical), rabbit Metazoa_SRP (34% identical). Paralogues in human: RN7SL448P (74% identical), Metazoa_SRP (73% identical), RN7SL2 (73% identical), RN7SL3 (73% identical), RN7SL627P (73% identical), RN7SL664P (73% identical), RN7SL709P (72% identical), RN7SL1 (72% identical), RN7SL177P (72% identical), RN7SL278P (72% identical), RN7SL620P (72% identical), RN7SL660P (72% identical), and 701 more.